ABCB1 (ATP binding cassette subfamily B member 1)
Diseases named in the same sentence as ABCB1 in open-access papers (continued):
Sharing a sentence is not in itself a finding about the gene and the disease.
epilepsy (continued). "Based on previous studies, rs1128503 (C1236T) and rs3789243 were selected as candidate SNPs of ABCB1 to investigate their relationship with the efficacy, safety, and blood concentration of VPA in the treatment of children with epilepsy." (PMID 38004402, 2023). "Cytokines that are upregulated in the brain of patients with epilepsy include IL1α, IL1β, IL6, and TNFα, all of which regulate blood-brain barrier ABCB1 and ABCG2." (PMID 36973040, 2023). "Collectively, our results suggested that KCNQ1OT1 contributes to AED resistance through the miR-138-5p/NF-κB/ABCB1 axis in HBMEC/PHT cells, and these results provide a promising therapeutic target for the treatment of medically intractable epilepsy." (PMID 31920517, 2019). "The impact of other neurological diseases such as epilepsy on the expression and function of the BBB drug transporters ABCB1 and ABCG2, as well as other efflux or influx transporters, may be different." (PMID 33916769, 2021). "While comparing the haplotypic association among the three well studied ABCB1 variants viz: rs1128503 (C1236T), rs2032582 (G2677T) and rs1045642 (C3435T) we observed that the TGT haplotype was strongly associated with epilepsy but not with AED resistance." (PMID 24586633, 2014). "Hence, the substitution of C to T at position 3435 of the exon 26 of the ABCB1 gene does not effect the response to AEDs in the epilepsy patients with different ethnicities." (PMID 21747587, 2011). "Up to 1/3 of patients with epilepsy do not respond to AED therapy and the transporter hypothesis proposes that over expression of efflux transporters such as ABCB1 in the blood–brain barrier limits access of AEDs to the epileptic focus." (PMID 33217013, 2021).
colorectal cancer (93 papers, 1995 to 2026). A primary or metastatic malignant neoplasm that affects the colon or rectum. "Another study conducted in Spain also linked ABCB1-rs1128503, rs2032582, and rs1045642 with a high risk of grade >2 diarrhea and overall toxicity upon capecitabine administration for colorectal cancer." (PMID 40894378, 2025). "Among certain populations, there is a correlation between ABCB1 gene polymorphisms and the risk for colorectal cancer, although it has also been shown that certain ABCB1 variants." (PMID 33163405, 2020). "The ATP-binding cassette transporters ABCG2 and ABCB1 have previously been associated with chemotherapy resistance, early disease recurrence and shorter survival in colorectal cancer." (PMID 28877221, 2017). "The aim of this investigation was to verify the possible contribution of ABCB1 single nucleotide polymorphisms (SNPs) to the genetic risk of colorectal cancer (CRC)." (PMID 25355168, 2014). "Compared to small molecule inhibitors, the novel CRISPR/Cas9‐gene editing approach has a great potential for future personalized therapy in treating ABCB1‐associated MDR colorectal cancer with an advantage to avoid drug‐drug interaction and toxicity from combinational chemotherapy." (PMID 34977876, 2021). "From the drug resistance spectrum of the cells, the effectiveness of common ABCB1 substrates, including doxorubicin, paclitaxel, docetaxel, vincristine, vinblastine, colchicine, and mitoxantrone, were negatively associated with the ABCB1 expression level in colorectal cancer cells." (PMID 34977876, 2021). "Abbreviations used: the ATP-binding cassette, subfamily B, member 1 (ABCB1); multidrug resistance gene 1 (MDR1); P-glycoprotein (P-gp); colorectal cancer (CRC); single nucleotide polymorphisms (SNPs); odds ratio (OR); confidence interval (CI); Hardy-Weinberg equilibrium (HWE)." (PMID 24353734, 2013). "We investigated the impact of ABCB1 genetic variants on colorectal cancer (CRC) risk." (PMID 22396794, 2012). "Recently, the use of SpCas9 to knockout ABCB1 in multidrug-resistant colorectal cancer cells (SW620/Ad300 and HCT-15) has demonstrated restored sensitivity to the ABCB1 substrate drug, doxorubicin." (PMID 40968311, 2025). "Mechanistically, RPF2 expression facilitates the binding of the RPF2‐CARM1‐MYCN trio and CARM1's association with the nucleus, which in turn boosts the expression of the downstream protein ABCB1, enhancing colorectal cancer resistance." (PMID 39964832, 2025). "Other researchers investigated the therapeutic potential of retinol as a modulator of ABCB1 gene expression in human colorectal cancer cell lines with varying ABCB1 expression levels: HT29 (very low ABCB1 expression) and SW620 (high ABCB1 expression)." (PMID 41303640, 2025). "In summary, our findings demonstrate that H89 reverses multidrug resistance in colorectal cancer by inhibiting the ATPase activity of ABCB1." (PMID 41462884, 2025). "While gene expression dropped just at 24 h, compound 1C selectively suppressed colorectal cancer cell growth and greatly lowered ABCB1 protein levels in COLO 320 cells at 24, 48, and 72 h." (PMID 40362377, 2025). "A study assessing the responses of colorectal cancer (CRC) to capecitabine and oxaliplatin regimen found that those with ABCB1 gene variants (rs1128503 and rs1045642) had better disease-free survival rate (DFSR) and overall survival rate (OSR)." (PMID 40813374, 2025). "The HDAC inhibitor sodium butyrate increases ABCB1 expression in lung and colorectal cancer cells by elevating H3K9ac levels through the inhibition of HDAC4." (PMID 40265153, 2025). "They suggested that the inhibition of NRF2/ABCB1 signaling (where ABCB1 is a regulatory gene for P-gp) can be considered as a novel strategy to improve the efficacy of chemotherapeutics against colorectal cancer." (PMID 37375797, 2023).
colorectal cancer (continued). "ABCB1 protein levels were observed to be lower in colorectal cancer tissue compared to normal tissue in the immunohistochemistry analysis performed on 51 cancer patients." (PMID 37895364, 2023). "A current study suggested that overexpression of IGF2BP3 in HCT8/T cell bound to the m6A site of ABCB1 and elevated ABCB1 expression, thereby reducing the sensitivity of colorectal cancer (CRC) cells to chemotherapy." (PMID 35843942, 2022). "Although it has been suggested in the literature that the inhibition of one abundant ABC transporter (e.g., ABCB1) is sufficient to reduce the growth of colorectal cancer cells, this was measured in this study." (PMID 36012706, 2022). "Compared to tons of EGFR inhibitors studied as ABCB1 reversal agents, MRTX849 showed good anticancer efficacy and safety in patients with non-small cell lung cancer and colorectal cancer with KRAS G12C mutation in clinical studies." (PMID 36104708, 2022). "We found that rhMG53 reduced cellular proliferation of both parental and ABCB1 overexpressing colorectal carcinoma cells." (PMID 36147477, 2022). "Colorectal cancer constitutively overexpressed P-glycoprotein (P-gp), which is encoded by the multidrug resistance gene (MDR1, ABCB1)." (PMID 33795638, 2021). "Overall, the present study suggests that the CRISPR/Cas9 system targeting the ABCB1 gene can be an effective approach to overcome ABCB1‐mediated MDR in colorectal cancer cells." (PMID 34977876, 2021). "In this study, the CRISPR/Cas9 system was utilized to target ABCB1 in MDR colorectal cancer SW620/Ad300 cell line with ABCB1 overexpression." (PMID 34977876, 2021). "Overall, the CRISPR/Cas9 system targeting the ABCB1 gene can be an effective approach to overcome ABCB1‐mediated MDR in colorectal cancer SW620/Ad300 cells." (PMID 34977876, 2021). "The ABCB1 expression is closely correlated with MDR in colorectal cancer, therefore, various approaches to suppress ABCB1 have been developed extensively investigated." (PMID 34977876, 2021). "ABCB1 is one of the mechanisms that induce tumor resistance, and it is usual high-expression in colorectal cancer." (PMID 33795638, 2021). "Accordingly, the ABCB1 overexpressing MDR human colorectal cancer cell line SW620/Ad300 along with its parental SW620 cell line, were selected in the present study." (PMID 34977876, 2021). "In this study, the CRISPR/Cas9 system was utilized to target ABCB1 in multidrug resistant (MDR) colorectal cancer SW620/Ad300 cell line with ABCB1 overexpression." (PMID 34977876, 2021). "In the present study, a CRISPR/Cas9 was applied to establish ABCB1 gene knockout cell models from an ABCB1 overexpressing MDR colorectal cancer cell line SW620/Ad300." (PMID 34977876, 2021). "To improve the current understanding of the MDR-1-related drug resistance in colorectal cancer, we explored gene co-expression networks around ABCB1 gene and repurposed candidate drugs for the treatment of CRC." (PMID 32903699, 2020). "Here we report the MACC1 dependent treatment resistance of colorectal cancer (CRC) cells to standard therapeutics like doxorubicin by upregulating ATP-binding cassette subfamily B member 1 (ABCB1) protein." (PMID 32391276, 2020). "Our findings suggest that digoxin has the potential to be applied as an antitumor drug via inhibiting proliferation and metastasis as well as reversing the ABCB1-mediated multidrug resistance of colorectal cancer." (PMID 33442480, 2020). "Nuclear factor-kappaB (NF-κB) was shown to regulate ABCB1 and inhibition of NF-κB was able to sensitize colorectal cancer cells to chemotherapy in an ABCB1 dependent way21." (PMID 32814794, 2020). "The purpose of this present study was to investigate the reversal effect of BU on ABCB1-mediated multidrug resistance in colorectal cancer." (PMID 28624793, 2017).
colorectal cancer (continued). "A score based on ABCB1-CDA polymorphisms efficiently predicts patients at high risk of severe overall toxicity (PPV, 54%; sensitivity, 43%) in colorectal cancer patients treated with regimens containing capecitabine." (PMID 25691056, 2015). "We evaluated the association between nine polymorphisms in MTHFR, CDA, TYMS, ABCB1, and ENOSF1 and adverse reactions, dose reductions, treatment delays, and overall toxicity in 239 colorectal cancer patients treated with capecitabine-based regimens." (PMID 25691056, 2015). "Based on in vitro proliferation data, a panel of colorectal cancer cell lines were ranked as sensitive or resistant and ABCB1 (P-gp) expression was evaluated by microarray for these cell lines." (PMID 23524533, 2013). "Colorectal cancers are often chemoresistant toward antitumour drugs that are substrates for ABCB1-mediated multidrug resistance (MDR)." (PMID 22460269, 2012). "Actually, it has been reported that inhibition of the Ras/ERK pathway also promotes ABCB1 protein degradation to diminish the cellular multidrug resistance in the human colorectal cancer cell lines." (PMID 20167130, 2010). "Furthermore, EMT transcription factors upregulate ABC transporter genes such as ABCB1 and ABCC1, increasing drug efflux; for example, Twist1 binds the ABCB1 promoter in colorectal cancer, driving irinotecan export and resistance." (PMID 41229498, 2025). "This study investigates H89 as a novel ABCB1-inhibitor to reverse MDR in colorectal cancer (CRC)." (PMID 41462884, 2025). "SAHA and TSA may increase the expression of ABCB1 in lung and colorectal cancer cells by downregulating HDAC3 or HDAC4." (PMID 40265153, 2025). "ABCB1 helps protect cells from toxic compounds but also contributes to multidrug resistance (MDR) in colorectal cancer cells by reducing the intracellular concentration of anticancer drugs, including doxorubicin, paclitaxel, and vincristine, making them less effective." (PMID 40791849, 2025). "Moreover, in colorectal cancers, overexpression of ABCB1 and ABCG2 has been documented with poor clinical outcome." (PMID 33593355, 2021). "Besides, a broader spectrum of drug sensitivity after knockout of the ABCB1 gene is yet to be evaluated in MDR colorectal cancer cells." (PMID 34977876, 2021). "IGF2BP3 could directly interact with the m6A-modified region on ATP-binding cassette transporters subfamily B member 1 (ABCB1) mRNA, resulting in the high expression of ABCB1 and the elevation of ABCB1 mRNA stability in colorectal cancer cells." (PMID 34657141, 2021). "The ABC transporter family member ABCB1 is often overexpressed in colorectal cancer (CRC)." (PMID 32056006, 2020). "Therefore, the aim of this study was to extensively investigate the association between genetic polymorphisms in CYP3A4/5, DPYD, UGT1A1, ABCB1, ABCC2, and ABCG2 and irinotecan induced-toxicity in cohort of Thai colorectal cancer patient." (PMID 32778670, 2020). "Taken together, our results indicated that BU could reverse ABCB1-mediated MDR in colorectal cancer cells." (PMID 28624793, 2017). "Overall, we concluded that BU efficiently reversed ABCB1-mediated MDR through not only inhibited the efflux function of ABCB1, but also down-regulate its protein expression, which might represent a potential and superior ABCB1 modulator in colorectal cancer." (PMID 28624793, 2017). "Although β-catenin/TCF4-mediated ABCB1 expression represents only one mechanism within the complex transcriptional regulation of the ABCB1 gene, our findings on the dominant action of gain-of-function β-catenin adds to the current knowledge on the role of ABCB1 in the biology of colorectal cancer." (PMID 22460269, 2012). "The last gene whose expression was repressed by radiation and further inhibited by melatonin was ABCB1, a protein involved in multidrug resistance, whose expression was induced by high doses of radiation but subsequently decreased significantly by low doses in colorectal cancer cells." (PMID 35625825, 2022).
colorectal cancer (continued). "According to the mRNA expression levels of ABCB1, ABCC1, and ABCG2 transporters in colorectal cancer patients, there is a significant difference in the expression levels of these ABC transporters." (PMID 41557172, 2026). "ABCB1, ABCC1, and ABCC2 mRNA levels were compared between Caco-2 cells and other colorectal cancer cell lines (HCT-15, LoVo, DLD-1, HCT-116, SW620)." (PMID 41557172, 2026). "To investigate the effect of H89 on ABCB1-mediated MDR in CRC cells, we initially evaluated the effect of H89 on colorectal cancer cell viability through cytotoxicity assays." (PMID 41462884, 2025). "OX@Se-MnP NPs reversed MDR in colorectal cancer by down-regulating the expression of MDR-related ABC (ATP binding cassette) transporters proteins (e.g., ABCB1, ABCC1 and ABCG2)." (PMID 36859296, 2023). "Expression analysis of prototypical PXR target genes ABCB1 and CYP3A4 in LS174T colorectal cancer cells and HepaRG hepatocytes revealed novel antagonists as selective receptor modulators, which showed gene- and tissue-specific effects." (PMID 35455978, 2022). "One of the critical mechanisms of MDR in colorectal cancer is the reduced intracellular drug level led by the upregulated expression of the ATP‐binding cassette (ABC) transporters, particularly, ABCB1/P‐gp." (PMID 34977876, 2021). "The intracellular accumulation of ABCB1 substrate [3H]‐paclitaxel and the drug efflux activity were measured to examine the effect of ABCB1 knockout on MDR colorectal cancer cells." (PMID 34977876, 2021). "Gedatolisib competitively increased the accumulation of tritium-labeled substrate-drugs in both ABCB1- and ABCG2-overexpression colorectal cancer cells." (PMID 33593355, 2021). "Among the members, ABCB1, also known as P‐glycoprotein (P‐gp), is one of the most common contributors to MDR in colorectal cancer." (PMID 34977876, 2021). "In present study, we evaluated the role of ABCB1 and ABCG2 in process of gedatolisib resistance in colorectal cancer cells." (PMID 33593355, 2021). "Although ABCB4 shares some similarity with ABCB1, the ABCB4 showed a different pattern in the colorectal cancer." (PMID 29371412, 2018). "P-gp, also known as ATP binding cassette subfamily B member 1 (ABCB1), is a membrane-bound efflux transporter that plays a critical role in the multidrug resistance (MDR) phenomenon observed in many cancers, including breast, ovarian, and colorectal cancers." (PMID 39274842, 2024). "The novel antagonists 73 and 100 demonstrated gene-specific effects in LS174T colorectal cancer cells, not inducing on their own the expression of ABCB1, but inducing CYP3A4 expression to a similar extent as rifampicin." (PMID 35455978, 2022). "This means that co-administration of gedatolisib with ABCB1 or ABCG2 inhibitors may have potential benefits to avoid gedatolisib resistance and improve the efficacy of gedatolisib in colorectal cancer." (PMID 33593355, 2021). "Moreover, gedatolisib significantly increased the protein expression level of ABCB1 and ABCG2 in colorectal cancer cells." (PMID 33593355, 2021). "Thus, the aim of this study was to assess the allele and genotype frequencies and the relationship between CYP3A4/5, DPYD, UGT1A1, ABCB1, and ABCC2 genetic variations and irinotecan-induced toxicity in Thai colorectal cancer patients." (PMID 32778670, 2020). "Notably, neither H89 nor verapamil enhanced the sensitivity of these two colorectal cancer cells to oxaliplatin (non-ABCB1 substrate drug)." (PMID 41462884, 2025). "The impact of ABCB1 expression on GAL1 levels in colorectal cancer cells is not yet understood." (PMID 40362377, 2025). "Hence, in present study, we focused on the effects of ABCB1 and ABCG2-mediated gedatolisib resistance in colorectal cancer cells, which may challenge its clinical administration effect." (PMID 33593355, 2021).
colorectal cancer (continued). "In addition, as our immunofluorescence results illustrated, gedatolisib did not significantly altered the subcellular localization of ABCB1 or ABCG2 in drug-resistant colorectal cancer cells." (PMID 33593355, 2021). "The established ABCB1 knockout colorectal cancer cell lines can be useful as models for studying ABCB1‐independent MDR mechanisms and discovering novel therapeutic approaches in future research to provide clues for overcoming multidrug resistance in colorectal cancer." (PMID 34977876, 2021). "However, at nearly non-toxic concentration, gedatolisib could not significantly reverse ABCB1- or ABCG2-medaited MDR in colorectal cancer cells, indicated that gedatolisib could not be a good reversal agent due to its relative high toxicity." (PMID 33593355, 2021). "In conclusion, ML210 can sensitize ABCB1-overexpressing multidrug-resistant colorectal cancer cells to ABCB1-substrate chemotherapeutic agents, indicating that ML210 is a promising ABCB1 inhibitor capable of antagonizing ABCB1- not ABCG2-mediated MDR in CRC." (PMID 40427071, 2025). "In human colorectal carcinoma Caco-2 cells, ATRA showed a dose-dependent inhibition of ABCB1 efflux activity, despite having no detectable effect on ABCB1 mRNA expression." (PMID 41303640, 2025). "First, we assessed the mRNA and protein expression patterns of ABCB1 in human specimens of CAC, in comparison to UC without colorectal cancer and CRC without UC, respectively." (PMID 28686677, 2017).